ESR1 (estrogen receptor 1)
Diseases named in the same sentence as ESR1 in open-access papers (continued):
Sharing a sentence is not in itself a finding about the gene and the disease.
breast cancer (continued). "In contrast to the ESR1 mutations, the PIK3CA mutations were not significantly more prevalent in ER + /HER2-disease compared to other breast cancer subtypes and 14% of the PIK3CA mutant samples had more than one PIK3CA mutation." (PMID 30083595, 2018). "Our WGCNA analysis revealed an unknown network between NF1, ESR1, and RAS signaling in breast cancer." (PMID 30182054, 2018). "Estrogen receptor alpha gene (ESR1) fusion transcripts have been identified in breast cancer but their role in breast cancer is not completely understood." (PMID 30525098, 2018). "Interestingly, molecular subtyping of breast cancers in the clinic is routinely based on immunohistochemical analysis of HER2-, ESR1- and PGR-expression from tumor biopsies and is rarely assessed at a transcriptional level." (PMID 30279965, 2018). "Moreover, we also show that mRNA abundance of both RET and GFRA1 correlate with ESR1 across primary breast cancers, suggesting that RET and GFRA1 are direct targets of ERα signaling in primary patients as well." (PMID 29608602, 2018). "In addition, four cytokeratin genes (KRT8, KRT16, KRT17, and KRT19) and eight tumor-associated genes (TERT, MUC16/M17S2/CA125, CD44, TWIST1, TACSTD1/EpCAM/CD326/ESA/HEA125/GA733, DPP4/CD26, ESR1, and PGR), were upregulated in CRC and breast cancer samples." (PMID 29882767, 2018). "Of those, FOXA1, ESR1 and GATA3 are not only reported as co-expressed and co-localized in breast cancer cells, but there is even strong evidence suggesting they might form an enhanceosome that regulates many genes involved in the ER signaling cascade." (PMID 29741575, 2018). "Here, we analyze 1246 invasive breast cancer samples from the Cancer Genome Atlas and show that human breast cancers that have been subtyped based on their HER2, ESR1, or PGR expression contain four clusters of genes that are differentially expressed across all subtypes." (PMID 30279965, 2018). "The gain of ESR1 methylation in PR-negative breast carcinomas was stronger at the gene promoter rather than within the gene body." (PMID 30301163, 2018). "DLEU1 is up‐regulated in MCF‐7 cells and might be coexpressed with miR‐19a to co‐regulate the expression of ER‐α (ESR1), which influences the occurrence and development of breast cancer." (PMID 28598010, 2017). "Accurate determination of the predictive markers human epidermal growth factor receptor 2 (HER2/ERBB2), estrogen receptor (ER/ESR1), progesterone receptor (PgR/PGR), and marker of proliferation Ki67 (MKI67) is indispensable for therapeutic decision making in early breast cancer." (PMID 28490348, 2017). "The present study provides methylation levels for the promoters of APC, BRCA1, CDKN2A, ESR1, ESR2, HER2/neu and PTEN, CDKN2A exon 2 and LINE-1 in tumor, tumor-adjacent and tumor-distant tissues from 18 breast cancer patients and normal breast tissues from four healthy women." (PMID 28403857, 2017). "Ten international pathology institutions participated in this study and determined messenger RNA expression levels of ERBB2, ESR1, PGR, and MKI67 in both centrally and locally extracted RNA from formalin-fixed, paraffin-embedded breast cancer specimens with the MammaTyper® test." (PMID 28490348, 2017). "ESR1 (estrogen receptor alpha), GATA3 (GATA Binding Protein 3), and CDH1 (E-cadherin) are amongst the genes most down-regulated by Twist expression and shown to be involved in the progression of breast cancer earlier." (PMID 28086829, 2017). "The overexpression of ESR1 and NOTCH1 is correlated with breast cancer progression and prognosis." (PMID 28793339, 2017). "We found no overlap (LD r2<0.17) between these five breast cancer signals and our four independent SNPs at the 6q25.1 (ESR1) locus." (PMID 28537267, 2017). "Compared with PDXs of non-luminal subtypes, luminal B breast cancer xenografts, as expected, showed higher mRNA and protein expression of ESR1 and PGR, consistent with their positive ER and PR status." (PMID 28348404, 2017).
breast cancer (continued). "Similar results were found in CCLE analysis, GATA3 over-expressed in the breast cancer cell lines with high level of ER expression, while under-expressed in those with low level or negative ESR1 expression (p<0.001)." (PMID 28423734, 2017). "In contrast to ESR1 only being expressed in CTCs of very few patients, HER2 gene expression at BL was found in seven out of 26 patients that were clinically diagnosed with HR+ breast cancer (e.g. Patient #3) or TNBC (Patient #8 and 33)." (PMID 28489591, 2017). "In the dataset of 50 breast cancer lines TF expression clustered with higher levels of basal-marker vimentin, keratin KRT5/14 and caveolin-1 (CAV1) but lower levels of luminal-marker keratin KRT8/18, ERBB3 and ESR1." (PMID 28938620, 2017). "Furthermore, MRTF/SRF target genes' expression was positively associated with basal marker (CDH3), but negatively correlated with luminal marker (ESR1), suggesting that the activity of MRTF/SRF is higher in basal-like breast cancers than other subtypes." (PMID 26885614, 2016). "Specific difference in ESR1 gene methylation has been found between normal and breast tumor-adjacent tissues, and between ERα-positive and ERα-negative breast cancer cells." (PMID 26980709, 2016). "In addition to the GATA3 motif, we also found that the GATA3-linked enhancers have known motifs of other transcription factors (e.g., FOXA, ESR1, TCF), which have been previously shown to work together with GATA3 in breast cancer." (PMID 27833659, 2016). "miR-222-3p, one of the top-ranked miRNAs detected in the model, has been shown to target the estrogen receptor 1 gene (ESR1) and was reported to be dramatically higher in ESR1 negative breast cancer cells, inhibiting ERα expression." (PMID 27833082, 2016). "Integrative data mining analysis was performed to plot the mean values of mRNA expression for ESR1 (ERα gene) and HYAL1 in the whole cohort and in each of the breast cancer subtypes, i.e. luminal A, luminal B, normal-like, basal-like and HER2, as classified by the PAM50 assay." (PMID 27764788, 2016). "This negative regulation of HYAL1 by ERα provides a mechanism supporting the specific inverse correlation we found between ESR1 and HYAL1, but not with HYAL2 or HYAL3 in the METABRIC cohort consisting of 1980 cases of breast cancer." (PMID 27764788, 2016). "In line with this, our data clearly demonstrate that KCNJ3 expression is associated with ER positive breast cancer and that KCNJ3 levels correlate with ESR1 mRNA expression levels but not with expression levels of other estrogen receptors." (PMID 27835900, 2016). "It is a regulator of the estrogen receptor 1 (ESR1) in ER positive breast cancer cells and interleukin 13Ra2 in ER negative breast cancer cells, regulating tumour growth, cell migration and metastasis." (PMID 27158822, 2016). "As one of the three most intensely scrutinized genes in breast cancer (the other two being ESR1 and HER2), there is no molecular mechanism of BRCA1 regulation that has not been examined in primary human breast cancer specimens." (PMID 27077368, 2016). "We found the ESR1 pathway, corresponding to endocrine response (GOZGIT) for MCF10A to MCF7, and the breast cancer cell line subtype characterization (CHARAFE) for MCF10A to MDA-MB-231, corresponding to EMT related genes, were correlated with differential H3K4ac enrichment." (PMID 26783963, 2016). "Our data highlighting that the expression of GLI1 correlates with ESR1, pS2 and GREB1 using a publicly available dataset, suggest that GLI1 may represent a gene with implications in breast cancer." (PMID 27689403, 2016). "Furthermore, cut-off values for receptor negative vs. positive tumors need to be established and have already been determined for ESR1 and PGR in human breast cancer using a bDNA assay." (PMID 27649560, 2016). "In breast cancer, CpG-island methylation was shown to inhibit PTCH1, EFEMP1 and ESR1 expression." (PMID 25986046, 2015).
breast cancer (continued). "To investigate whether ncRNA production in LTED cells is specific to the ESR1 locus, we examined the ERBB2 gene that plays a role in a subset of breast cancers." (PMID 25923108, 2015). "In addition, MIR17HG overexpression was found to inhibit proliferation of luminal breast cancer cells by targeting a steroid receptor coactivator (NCOA3), cyclin D1 (CCND1) and estrogen receptor α (ESR1)." (PMID 25069832, 2014). "Estrogen receptor‐negative human breast cancer cells inactivate the promoter of the ESR1 gene by methylation of its CpG island." (PMID 24963031, 2014). "In agreement with the largest meta-analyses of epidemiological studies to date, we did not observe an association for SHBG rs6259, PGR rs1042838, ESR1 rs2234693, CYP19 rs10046 and rs4775936, and UGT1A1 rs8175347 and breast cancer risk." (PMID 23935996, 2013). "Amplification of the ESR1 gene, coding for estrogen receptor alpha, was shown to predict responsiveness to tamoxifen, however its prognostic impact in breast cancer patients has not been thoroughly investigated." (PMID 23951298, 2013). "Recently, some authors described the effect of the addition of HDAC-inhibitors to restore the efficiency of endocrine therapy, for example through re-expression of ESR1 mRNA by trichostatin A or Valproate in ESR1 negative breast cancer cells." (PMID 23627572, 2013). "It has recently been proposed that a three-gene model (SCMGENE) that measures ESR1, ERBB2, and AURKA identifies the major breast cancer intrinsic subtypes and provides robust discrimination for clinical use in a manner very similar to a 50-gene subtype predictor (PAM50)." (PMID 22752290, 2012). "In addition to being significantly coregulated with ESR1 expression, the present results suggest that there is greater mRNA expression level of PRSS23 in breast cancer specimen than other well-known cancer-related proteases." (PMID 22291950, 2012). "For example, the androgen (AR) and estrogen (both ESR1 and ESR2) nuclear hormone receptors are known to be relevant in prostate and breast cancers, and the alpha-type platelet-derived (PDGFRA) and epidermal (EGFR) growth factor receptors are recognised angiogenesis factors." (PMID 22558171, 2012). "ESR1 and GSTP1 methylation could be important in the development of these high-grade male breast cancers." (PMID 22765268, 2012). "The miR-206 is upregulated in estrogen receptor negative (ER−) breast cancers and also inhibits the expression of the estrogen receptor gene ERα (ESR1) through two binding sites in the ESR1 3′ UTR." (PMID 23202960, 2012). "In the study presented herein, we show ribavirin to induce the re-expression of functionally active ESR1 in ESR-negative breast cancer cells." (PMID 22414275, 2011). "In vitro studies identified the HDAC inhibitor Trichostatin A (TSA) to restore functional ESR1 mRNA and protein expression in ESR1 negative breast cancer cells." (PMID 22414275, 2011). "FOXA1, ESR1 and UBE2C, are known as breast cancer prognosis biomarkers." (PMID 21806811, 2011). "Specifically, we have focused on comparison of a panel of breast cancer cell lines that either express or do not express estrogen receptor-α (the product of the ESR1 gene, hereinafter called ER)." (PMID 21364760, 2011). "Up to date, all currently available gene signatures have failed to discriminate oestrogen receptor (ESR1)-negative/HER2-negative breast cancer with poor prognosis from those with relatively good outcome." (PMID 20736952, 2010). "In our in silico analysis, we recently showed that, apart from repressing MYC, ras, and HMGA2, let-7 may also target CYP19A1, ESR1, and ESR2, thereby potentially blocking estrogen signalling in er-positive breast cancers." (PMID 20179807, 2010). "While this manuscript was under revision, another group published that the Sin3 complex represses the ERα gene, ESR1, in ERα-negative breast cancer cell lines." (PMID 20920219, 2010).
breast cancer (continued). "Median PMR values of APC and RASSF1A, but not of ESR1, were significantly higher among breast cancer cases as compared with controls (P<0.05)." (PMID 19367284, 2009). "As a result of these advances, a breast cancer cluster with poor prognosis that is negative for the estrogen receptor (ESR1), the progesterone receptor (PRGR) and ERBB2 (triple negative) has come to the forefront of medical therapeutic attention." (PMID 19007432, 2008). "The α subunit of the estrogen receptor (ESR1) is degraded by the UPS, and compounds inhibiting its degradation could accelerate breast cancer growth." (PMID 19007432, 2008). "Despite the fact that there are no mouse models of ERBB2 and ESR1 function in breast cancer, there is good potential for novel models to be generated for dissecting the roles of these two proteins." (PMID 19007432, 2008). "The combined dataset profile included two known molecular markers of breast cancer: BCL2 and ESR1." (PMID 17883867, 2007). "SNAI2 promotes ESR1 methylation by recruiting DNA methyltransferase 3B rather than DNA methyltransferase 1 in ERα-positive breast cancer cells and may contribute to cell adhesion and junctions." (PMID 39781343, 2025). "The convergence of these findings highlights the robustness of ESR1 and MAPK/JNK signaling as central processes in the 3D culture system, providing more substantial evidence that these pathways are critical in modulating the behavior of breast cancer cells in three-dimensional environments." (PMID 41163216, 2025). "In our study, all three PAEs showed a strong and stable binding with ESR1 and PPARA through strong binding force or extensive hydrogen bonding assistance, suggesting that these receptors may be primary targets through which breast cancer is promoted." (PMID 41155171, 2025). "Interestingly, miR-18a-5p expression in ER + breast cancer tissues showed a negative correlation with ESR1 transcripts and ER protein, a finding also reflected in our enrichment analysis, which revealed the activation of this pathway." (PMID 41163216, 2025). "However, MDA-MB-453 cells are classified as ERα negative breast cancer cells, and treatment with calcium induced the expression of ESR1 (~3.6-fold) that was blocked by DES." (PMID 41516107, 2025). "Our findings demonstrated that depletion of RAD51B by CRISPR/Cas9 enhanced the recruitment of PRC2 to Esr1 promoter and resulted in the modification of H3K27me3 in this region, leading to the repression of ERα protein and the switch from ERα-positive breast cancer to an ERα-negative type." (PMID 41318657, 2025). "While GATA3, ESR1, PIK3CA, FOXA1, FOXO3, and RB1 protein abundances were not significantly reduced in GATA3mut breast cancers, the expression of genes associated with MDM2 function and phosphorylation of genes associated with ERK signaling and aggressive phenotypes were impacted." (PMID 40439821, 2025). "Among TNBC stage I-III breast cancers with early (N = 134) and late (N = 66) recurrence, the most frequent alteration was PIK3CA (20.2% vs 33.3%), followed by BRCA1/2 (6.0% vs 9.1%), PD-L1 amplification (2.2% vs 3.0%), PALB2 (1.5% vs 0%), and ESR1 (0% vs 1.5%)." (PMID 40421962, 2025). "Additionally, CXCL6 gene expression and ESR1 showed a negative significant (p < 0.05) correlation in breast cancer Her2 and Luminal A patients." (PMID 39201290, 2024). "To evaluate whether this data-driven cutoff may be generalisable to other cohorts and thus a feasible clinical strategy, we assessed the distribution of ESR1 and PGR expression in an independent cohort of metastatic breast cancer that includes GEX data from primary tumours and distant metastases." (PMID 38587062, 2024).
breast cancer (continued). "Furthermore, the panel used in this study did not include the RB gene, which was thought to predict the efficacy of CDK4/6 inhibitors, or the ESR1 or PIK3CA genes, which were frequently observed in breast cancer and were considered involved in endocrine therapy resistance." (PMID 38539518, 2024). "There was indeed a positive correlation between HOXB2 and both ESR1 and PGR, allowing the conclusion to be drawn that low expression of HOXB2 could lead to the transition of ER+ and/or PR+ breast cancers to express less hormone receptors, and display more aggressive phenotypes like TNBC." (PMID 38322121, 2024). "Additionally, clinical data revealed a positive association between ESR1 and S100A14 gene expression in patients with Basal and Her2 breast cancer, but a negative correlation in patients with Luminal A and Luminal B breast cancer." (PMID 39594999, 2024). "For instance, the APP (amyloid-beta precursor protein), ESR1 (estrogen receptor 1), TUBB (beta tubulin), and CUL3 (culin-3) genes have established links to promoting cancer cell survival, adhesion, differentiation, migration, and resistance to therapy in breast cancer." (PMID 38378612, 2024). "All MaPR245W/− mammary tumors were TNBC lacking Esr1, Pgr, or Erbb2 expression." (PMID 38994678, 2024). "Interaction of YAP1 and ESR1 in nuclei is a unique feature of HR+HER2− breast cancer, and thus YAP1 could serve as a prognostic marker as well as a therapeutic target in patients with HR+HER2− breast cancer." (PMID 37894401, 2023). "Presence of ESR1 mutations in baseline ctDNA might not be associated with inferior PFS and OS in advanced breast cancer patients treated with paclitaxel/bevacizumab." (PMID 37226020, 2023). "Estrogen receptor alpha (ESR1)-negative breast cancer shows minor sensitivity to hormone therapy." (PMID 37569824, 2023). "Sesamol re-expressed ESR1 to inhibit ESR1-negative breast cancer cells by upregulating miR-370-3p." (PMID 37569824, 2023). "In patients with breast cancer, the negative correlation between methylation and ESR1 induction of gene expression involved mostly CpGs located at enhancers >1 kbp downstream of the transcription start site, corresponding with the location of the intronic enhancer of Srd5a1." (PMID 37646011, 2023). "Since the protein product of ESR1, ERα, is the main driver of estrogen‐target gene transcriptional activation, ER+ breast cancer development, and endocrine drug resistance, we proposed that LINC02568 might regulate the expression of ESR1 to exert its functions in such aspects." (PMID 37404090, 2023). "Furthermore, the results from our WGCNA analysis indicated the existence of unknown networks between INO80 and a subset of luminal breast cancer biomarkers, including FOXA1, ESR1, GATA3, TFF1, and AR." (PMID 38020889, 2023). "Our study reveals that unlike ESR1, PGR is associated with gene silencing in canine mammary tumors." (PMID 37034591, 2023). "In breast cancer cells, the accumulation of misfolding-prone proteins in the mitochondrial intermembrane space (IMS) interferes with ETC homeostasis, leading to an increase in the level of ROS in the IMS and subsequently triggering the activation of estrogen receptor α (ERα or ESR1)." (PMID 35180892, 2022). "Although CA12 is regulated in breast cancer cells by other transcription factors (TFs) such as AP2γ and by hypoxia, albeit much less than its paralog CA9, we show that its RNA expression levels are amongst the most highly correlated with those of the ESR1 gene in several transcriptome datasets." (PMID 36358871, 2022). "In ERα-negative breast cancer cells, HDAC1 contributes to the inactivation of the esr1 promoter." (PMID 34604071, 2021). "Notably, to date, a comprehensive miRNA-mRNA regulatory network involved in modulation of ESR1 in development and progression of ERα positive breast cancer is still not established." (PMID 32500028, 2020).